MDH2 (malate dehydrogenase 2)
Diseases named in the same sentence as MDH2 in open-access papers (continued):
Sharing a sentence is not in itself a finding about the gene and the disease.
brain injury (1 paper, 2023). Acute and chronic (see also brain INJURIES, CHRONIC) injuries to the brain, including the cerebral hemispheres, CEREBELLUM, and brain STEM. "For example, the lncRNA U90926 directly binds to malate dehydrogenase 2 (MDH2), which could aggravate ischaemic brain injury by facilitating neutrophil infiltration." (PMID 36880874, 2023).
cardiomyopathy (1 paper, 2018). A disease of the heart muscle or myocardium proper. "MDH2 druggability has been studied in the context of doxorubicin-induced cardiomyopathy, where the non-specific MDH2 inhibitors mebendazole, thyroxine, and iodine have been found promising." (PMID 29563510, 2018).
colorectal tumor (1 paper, 2024). "Proteins that regulate glycolysis (PGK1, PGAM1, ENO1, PKM, TKT), ammonia detoxification (GLUD1), and other metabolic pathways (LDHA, GAPDH, MDH2) were reported to be differentially expressed in mouse xenograft colorectal tumor models with different radio- responsiveness." (PMID 38410100, 2024).
glucose metabolism disorders (1 paper, 2022). "Given that the proteins PFKM, GAPDH, ACO2, and MDH2 have rate-limiting effects on aerobic oxidative metabolism, the decreased expression is consistent with the results of glucose metabolism disorders in diabetic patients." (PMID 36187097, 2022).
heart failure (1 paper, 2024). Inability of the heart to pump blood at an adequate rate to meet tissue metabolic requirements. "At these ratios, they regulated the protein levels of the downstream players of the Ca2+ signaling pathway via MDH2 and CALR, thereby balancing Ca2+ homeostasis in the myocardial tissue and mitigating the effects of heart failure." (PMID 39545061, 2024).
Hepatic fibrosis (1 paper, 2025). The presence of excessive fibrous connective tissue in the liver. "Liver specific Mdh2 knockdown eliminated Gli’s beneficial effects in naturally aged mice, reducing p16INK4a expression and hepatic fibrosis." (PMID 39962087, 2025).
liver disease (1 paper, 2024). "To conclude, in the present work we successfully generated an MDH2D liver disease model recapitulating disease-associated features such as reduced MDH2 expression and impaired flux through the MAS and the TCA cycle." (PMID 38425868, 2024).
major depressive disorder (1 paper, 2015). An episode of depression lasting two or more weeks without an intervening episode of mania. "The AD-associated proteins that we chose to further investigate included PCLO, which is associated with major depressive disorder (MDD); MDH2, which has been shown to regulate oxidative stress; and TRRAP, which plays an important role, together with Fe65, in AD." (PMID 26059363, 2015).
Methylmalonic aciduria (1 paper, 2022). Increased concentration of methylmalonic acid in the urine. "Decreased protein levels of malate dehydrogenase 2 were detected in a mouse model of methylmalonic aciduria, an inborn metabolic disorder of propionate catabolism that may lead to metabolic stroke and renal insufficiency." (PMID 36159820, 2022).
muscular dystrophy (1 paper, 2014). Muscular dystrophy (MD) refers to a group of more than 30 genetic diseases characterized by progressive weakness and degeneration of the skeletal muscles that control movement. "Comparison of the two muscular dystrophy phenotypes, DMD and BMD, in the UNEW cohort revealed again CA3 as an important contributor for the separation of these two patient groups and MDH2 and MYL3 for separation of the BMD patients and female carriers in both blood preparation types." (PMID 24920607, 2014).
myeloma (1 paper, 2023). "In addition, MDH2, MPC2, PAXIP1, and NSDHL were upregulated in myeloma patients." (PMID 37333985, 2023).
myocardial hypertrophy (1 paper, 2025). "Secondly, Mdh2 is localized to the mitochondria and may play pivotal roles in the malate–aspartate shuttle process, which is closely related to the occurrence of myocardial hypertrophy." (PMID 40281739, 2025).
renal carcinoma (1 paper, 2024). A carcinoma arising from the epithelium of the renal parenchyma or the renal pelvis. "We found that knockout of MDH2 conferred resistance to ferroptosis in renal cancer cells, and reduced morphological changes." (PMID 39138167, 2024). "This study revealed a significant decrease in MDH2 expression in renal cancer tissues." (PMID 39138167, 2024). "Moreover, opposite effects were observed in renal cancer cells with stable overexpression of MDH2." (PMID 39138167, 2024).
renal cell carcinoma (1 paper, 2022). "In renal cell carcinoma, inhibition of the glutamine-MDH2 axis suppresses in vitro tumor phenotypes in an L-2-HG-dependent manner." (PMID 36159820, 2022).
Respiratory insufficiency (1 paper, 2014). "Interestingly, patients with respiratory insufficiency have lower levels of TNNT3, MDH2, and ETFA than the ones without, suggesting that patient sub-groups within the DMD cohort could be identified." (PMID 24920607, 2014).
sarcoidosis (1 paper, 2025). Sarcoidosis is a multisystemic disorder of unknown cause characterized by the formation of immune granulomas in involved organs. "Among them, there were 14 genes (ABT1, BTN2A2, C2orf74, CCDC88B, FAM213A, MDH2, METTL21B, PRSS16, RP3-473L9.4, TCF19, TSFM, UBASH3A, UQCC2, ZSCAN26) associated with sarcoidosis risk consistently across these tissues." (PMID 40075078, 2025). "In addition, our TWAS pinpointed many tissue-specific sarcoidosis-associated genes and found expressions of 14 genes (ABT1, BTN2A2, C2orf74, CCDC88B, FAM213A, MDH2, METTL21B, PRSS16, RP3-473L9.4, TCF19, TSFM, UBASH3A, UQCC2, ZSCAN26) associated with sarcoidosis across all three target tissues." (PMID 40075078, 2025).
serous ovarian cancer (1 paper, 2025). "In high-grade serous ovarian cancer (HGSOC) patient samples, ZDHHC18-mediated palmitoylation of malate dehydrogenase 2 (MDH2) at Cys138 enhances its enzymatic activity." (PMID 40977744, 2025).
TCA cycle disorders (1 paper, 2025). "Here, we show that impaired expression of IDH3G and MDH2, resulting in reduced α-KG levels and upregulated fumarate levels, is an important manifestation of PD TCA cycle disorders and the metabolic basis for mitochondrial-driven PD pathogenesis." (PMID 40730642, 2025).
type 2 diabetes mellitus (1 paper, 2018). A type of diabetes mellitus that is characterized by insulin resistance or desensitization and increased blood glucose levels. "Glycolysis (triosephosphate isomerase 1 and phosphoglycerate kinase 1), citrate cycle (citrate synthase and malate dehydrogenase 2) and type II diabetes mellitus (pyruvate kinase) were among the other pathways identified for these proteins." (PMID 30419808, 2018).
varicocele (1 paper, 2020). A condition characterized by the dilated tortuous veins of the spermatic cord with a marked left-sided predominance. "The underexpressed proteins in the bilateral varicocele group compared to overexpressed proteins in unilateral varicocele were either low or very low and moderately abundant except for ENO1 and MDH2, which were highly abundant." (PMID 32365753, 2020).
cancer (35 papers, 2014 to 2026). A tumor composed of atypical neoplastic, often pleomorphic cells that invade other tissues. "Recently, MDH2 was associated with several type of cancer in which MDH2 expression levels were found increased." (PMID 31881713, 2019). "In contrast, ENO3, IDH2, IDH3G, and MDH2, genes that encode proteins that generally represses the proliferative, migratory, and invasive capacities of cancer cells, displayed the strongest positive correlations across nearly all cancers." (PMID 40806276, 2025). "Thus, mutations in MDH2 have multiple functions in modulating cell growth and can inhibit or stimulate cancer growth by deregulating the citric acid cycle." (PMID 38136396, 2023). "Recently, several studies have reported cancer-associated functions of MDH2." (PMID 27611801, 2016). "Modulating tumor metabolism strongly suggests that MDH2 is an innovative and attractive target for cancer treatment." (PMID 41179294, 2025). "Several studies have reported the successful development of small-molecule inhibitors targeting MDH2 to inhibit cancer metabolism and tumor growth, which have been applied in colorectal cancer research." (PMID 41179294, 2025). "Several small-molecule MDH2 inhibitors have been successfully developed, expanding the scope of novel cancer metabolism and tumor growth therapies." (PMID 41179294, 2025). "To further analyze MDH2 expression patterns, we combined data from the TCGA and GTEx databases, which revealed that MDH2 mRNA was significantly highly expressed in 25 cancer types, including BRCA, and significantly less expressed in 4 cancer types." (PMID 41179294, 2025). "As the KEGG enrichment analysis revealed, “central carbon metabolism in cancer” was significantly enriched in sh-Scr cells treated with Gli, while knockdown of Mdh2 expression nullified the effects of Gli." (PMID 39962087, 2025). "It is found that ER stress can regulate crucial enzyme (MDH2 and FH) activities of metabolic cascade in cancer cells, boosting aerobic respiration to attenuate the Warburg effect and promote cell apoptosis." (PMID 38483955, 2024). "We propose that PSMA1 knockdown alone leads to increased protein levels of MDH2, thereby exerting cancer-promoting functions." (PMID 36527092, 2022). "It has been considered that MDH2 is a potential molecular target for cancer therapy, and several chemical compounds have been reported as inhibitors of MDH2." (PMID 36139014, 2022). "The presence of a high amount of mitochondrial citrate, required to activate the forward work of MDH2 in the mitochondrial matrix, should be beyond doubt in cancer cells." (PMID 35178152, 2022). "MDH2 is a possible target in cancer therapeutics due to its effect on ATP production and drug sensitivity during knockdown." (PMID 31817761, 2019). "First, a novel MDH2 inhibitor, compound 7, was identified as potential anti-cancer drug, which validates MDH2 as a promising therapeutic target of cancer." (PMID 27611801, 2016). "In attempt to identify a compound targeting MDH2 for anti-cancer therapy, we performed virtual screening of a compound library." (PMID 27611801, 2016). "Although the functions of most metabolites in tumors remain unclear, our findings suggest that MDH2, as a mitochondrial metabolic enzyme, substantially alters the metabolic pattern of cancer cells and influences tumor progression." (PMID 41179294, 2025). "We next evaluated the expression pattern of MDH2 mRNA across various cancers using data from TCGA." (PMID 41179294, 2025). "The proportion of MDH2‐positive BxPC3 cells and Panc1 cells was 31% and 69%, while the proportion of FH‐positive BxPC3 cells and Panc1 cells was 57% and 88%, respectively, indicating higher energy production and altered hyperactive metabolism in cancer cells." (PMID 38483955, 2024). "ER stress could affect crucial enzyme (MDH2 and FH) activity of metabolic cascade in cancer cells, boosting aerobic respiration and attenuating the Warburg effect to promote cell apoptosis." (PMID 38483955, 2024).
cancer (continued). "Our results showed that the expression of FH and MDH2 were generally upregulated in cancer cells." (PMID 38483955, 2024). "Notably, treatment of cancer cells with an Mdh2 inhibitor induces downregulation of oxidative phosphorylation, which is in line with the role in the metabolic switch of Mdh2." (PMID 37074814, 2023). "Differentiation-inducing factor-1 (DIF-1) secreted from Dictyostelium discoideum, which was known to inhibit the proliferation of several cancer cells by downregulation of the Wnt/β-catenin signaling pathway, revealed its binding to MDH2 and inhibiting its activity." (PMID 36139014, 2022). "MDH2 has been implicated as a PCa biomarker by several proteomics, genomics, and functional studies, although its role in cancer, and specifically in PCa, has not been explained so far." (PMID 36553191, 2022). "Previous studies have provided concrete evidence that the inhibition of MDH2 might provide a valuable platform for developing novel therapeutics that target cancer metabolism and tumor growth." (PMID 36527092, 2022). "Therefore, MDH2 inhibition provides a valuable platform for developing novel therapeutics that target cancer metabolism and tumor growth." (PMID 36527092, 2022). "Indeed, the regulation of MDH2 activity was proposed as target to mediate resistance cancer cells to chemotherapy." (PMID 31881713, 2019). "Although there is no indication of cancer susceptibility in either family with MDH2 mutations, we are recommending ongoing surveillance and screening." (PMID 27989324, 2017). "This study has provided clear evidence that MDH2 inhibitors exert anti-cancer activity, and compound 7 could be used to develop an anti-cancer drug to regulate cancer metabolism." (PMID 27611801, 2016). "Recently, MDH2 has been recognized as an attractive target for cancer treatment." (PMID 27611801, 2016). "Furthermore, MDH2 inhibition by small-molecule compound 7 leads to a decrease of mitochondrial respiration by the reduction of NADH levels, implying that MDH2 is a potential target in cancer therapeutics due to its effect on ATP production and chemotherapy resistance." (PMID 35006438, 2021). "Moreover, a novel MDH2 inhibitor Compound 7 identified by virtual screening also demonstrated strong anti-tumor activity, suggesting MDH2 as a prospective therapeutic target of cancer." (PMID 27611801, 2016). "The MDH2 and EIF4H genes show important roles in cancer growth and metastasis; thus, they are of clinical importance for cancer treatment." (PMID 36109686, 2023). "Therefore, inhibitors of MDH2 may be useful in mediating cancer cell resistance to chemotherapy." (PMID 27611801, 2016). "Five enzymes (LDHB, MDH2, PKM2, AKR1B1, and AKR1B10) out of 40 enzymes in pyruvate metabolism pathway are overexpressed in cancer." (PMID 25243088, 2014). "Additionally, fatty acid metabolism‐related genes, including Acaa2, Mdh2 and Ech1, as well as oxidative phosphorylation‐related genes, such as Sdhc, Cox5a and Mdh1, also upregulated in KAR cancer cells." (PMID 40621620, 2025). "The upregulation of FH and MDH2 is higher in HPDE than in SW1990 cells, which may be related to the enhanced anaerobic glycolysis phenotype in cancer cells." (PMID 38483955, 2024). "Taken together, our study reveals a new role of MDH2 in HCC ferroptosis and progression via regulating GPX4, and MDH2, which is highly expressed in HCC, may upregulate GPX4 to mediate ferroptosis evasion, leading to the failure of clinical cancer treatment." (PMID 39519171, 2024). "MDH2 has not been a popular cancer-related target of interest, unlike fumarate hydratase (FH), succinate dehydrogenase (SDH) and isocitrate dehydrogenase (IDH)." (PMID 27611801, 2016). "Taken together, a novel MDH2 inhibitor, compound 7, suppressed HIF-1α accumulation via reduction of oxygen consumption and ATP production, integrating metabolism into anti-cancer efficacy in cancer cells." (PMID 27611801, 2016).
cancer (continued). "Due to the role of MDH2 in the TCA cycle in the mitochondrial matrix, we assessed whether compound 7 affects mitochondrial respiration in cancer cells." (PMID 27611801, 2016). "Based on these findings, we hypothesize that inhibiting MDH2 could modulate tumor growth and metastasis by disrupting the NAD/NADH equilibrium and malate-aspartate transport between the cytoplasm and mitochondria, thereby altering the energy metabolism of cancer cells." (PMID 41179294, 2025).
tumor (35 papers, 2009 to 2025). "To gain insight into the biological processes underlying MDH2-driven tumor progression, we identified significantly overrepresented gene ontology (GO) terms for clusters of DEGs." (PMID 41179294, 2025). "To further elucidate the downstream molecular mechanisms underlying MDH2’s effects on tumor growth, we conducted RNA sequence analysis to investigate the transcriptome of MDH2-OE MDA-MB-231 cells." (PMID 41179294, 2025). "Several studies reported germline mutations in other susceptibility genes for PPGLs, such as FH, SLC25A11, and MDH2, which were associated with aggressive tumor behavior." (PMID 34833055, 2021). "Finally, we conducted an in-depth investigation into the precise mechanisms underlying the impact of MDH2 on tumor growth and its influence on ferroptosis sensitivity in ccRCC." (PMID 39138167, 2024). "Given that the EMT is a key event in tumor migration initiation, we examined the effect of MDH2 on EMT markers in MDA-MB-231 cells." (PMID 41179294, 2025). "The Cox proportional hazards model was then employed to further explore the clinical significance of MDH2 expression in tumor immune subgroups." (PMID 41179294, 2025). "Further transcriptomic analysis revealed that MDH2 overexpression altered signaling pathways known to modulate tumor metastasis, including ribosome biogenesis, PI3K-Akt, NF-kappa B, and Rap1 signaling pathways." (PMID 41179294, 2025). "GSCs, responsible for tumor growth and drug resistance, rely on the high activity of malate dehydrogenase 2 (MDH2) to maintain their malignant phenotype." (PMID 40255400, 2025). "The results showed a significant decrease in the expression of MDH2 in tumor tissues compared to normal tissues." (PMID 39138167, 2024). "The results demonstrated that the levels of MDH2 mRNA and protein were lower in ccRCC tumor tissues compared to normal tissues." (PMID 39138167, 2024). "Due to its significant role in the TCA cycle, MDH2 attracts widespread attention, and researchers found that it plays a pivotal role in tumor growth, metastasis, and chemotherapy resistance." (PMID 39519171, 2024). "We observed varying intensities of MDH2 staining in both tumor tissues and their corresponding adjacent non-tumor tissues." (PMID 39138167, 2024). "Through IHC analysis of GIST tissues, we found low expression of TRIM21 and high expression of MDH2 in resistant tumor tissues." (PMID 38973363, 2024). "It showed that compared to the NC group, the MDH2 knockout group had a significantly faster tumor growth rate, as well as increased tumor weight and volume." (PMID 39138167, 2024). "Alcohol dehydrogenase 1A (ADH1A), CAT, GAPDH, and MDH2 were related to the generation of precursor metabolites and energy, which played an important role in the proliferation of tumor cells." (PMID 37124724, 2023). "The tumor-suppressive effects of methyl 3-(3-(4-(2,4,4-trimethylpentan-2-yl)phenoxy)propanamido)benzoate were investigated and demonstrated that dual inhibition of MDH1 and MDH2 is an effective approach to target tumor metabolism." (PMID 36968582, 2023). "This phenotype seems to be involved in tumor progression and mutations in the FH, SLC25A11, and MDH2 genes along with SDHB and SDHD mutations can be considered to be a risk factor for PPGL malignancy." (PMID 34833055, 2021). "In vivo, MDH2 overexpression accelerated xenograft tumor growth." (PMID 41179294, 2025). "In vivo, we dynamically monitored tumor growth driven by MDH2 overexpression." (PMID 41179294, 2025). "Collectively, these findings suggest that MDH2 may promote tumor metastasis by modulating these pathways and genes." (PMID 41179294, 2025). "Moreover, we observed a significant downregulation of MDH2 expression in ccRCC tissues as compared to their adjacent non-tumor tissues." (PMID 39138167, 2024). "The present study reveals a significant downregulation of MDH2 expression in ccRCC tumor tissues." (PMID 39138167, 2024).